FBXW7 (F-box and WD repeat domain containing 7)
Diseases named in the same sentence as FBXW7 in open-access papers (continued):
Sharing a sentence is not in itself a finding about the gene and the disease.
breast cancer (continued). "For instance, cophosphorylation of Serum/glucocorticoid-regulated kinase 3 (SGK3) with GSK-3β enhances the binding of FBXW7 to metastasis suppressor N-Myc downstream regulated gene 1 (NDRG1) and promotes NDRG1's ubiquitination, increasing breast cancer invasion and metastasis." (PMID 37658431, 2023). "FBXW7 and PTEN works together to inhibit breast cancer progression by suppressing mTOR." (PMID 31064356, 2019). "In breast cancer, the level of FBXW7 mRNA is comparatively lower than in normal tissues and is associated with poorer prognosis." (PMID 30791487, 2019). "Moreover, in breast cancer cells with high levels of PIN1, NOTCH1 signaling is strongly activated despite presence of FBXW7, inciting expansion of breast cancer stem cells (CSC) and tumorigenesis." (PMID 30873382, 2019). "We conclude that FBXW7 regulates the response to paclitaxel by targeting MCL1 and PLK1 in breast cancer cells and thus targeting these substrates may be a valuable adjunct for paclitaxel treatment." (PMID 27409838, 2016). "We sought to investigate the role of FBXW7 in the response to paclitaxel in breast cancer cells and in patients with node-negative disease." (PMID 27409838, 2016). "Moreover, inactivation of Fbxw7 attenuates TGF β-dependent regulation of cell growth and migration of breast cancer." (PMID 23826080, 2013). "In summary, we have identified a previously not recognized mechanism for inactivation of FBXW7/hCDC4 expression, namely promoter specific methylation with potential prognostic significance in breast cancer." (PMID 21122106, 2010). "We next analyzed FBXW7/hCDC4-β methylation in two cohorts of breast cancer specimens in which RNA was available and FBXW7/hCDC4 mRNA expression could be analysed." (PMID 21122106, 2010). "The immortalized breast epithelial cell lines IME and MCF10, expressed high levels of FBXW7/hCDC4-β compared to some breast cancer cell lines with low or absent FBXW7/hCDC4-β expression (left)." (PMID 21122106, 2010). "Interestingly, while NF-κB interacts with and amplifies C/EBPδ in cancer cells, FBXW7, which is controlled by C/EBPδ, in turn triggers ubiquitination and destruction of NF-κB via GSK-3 phosphorylation, inhibiting the NF-κB cascade response in breast cancer." (PMID 37658431, 2023). "Given the lack of an effective solution to breast cancer's clinical drug resistance dilemma, elucidating FBXW7's mechanism of action could provide a theoretical basis for targeted drug exploration." (PMID 37658431, 2023). "Unexpectedly, in our study, FBXW7 inactivation via siRNA-based knockdown or CRISPR/Cas9-based knockout significantly induced senescence in lung cancer (A549 and H460), colon cancer (HCT116), breast cancer (MCF7), and osteosarcoma (SJSA) cells, suggesting that this is a common phenomenon." (PMID 36104351, 2022). "The studies have found that FAM83D could not only affect cell proliferation and motility through the tumor suppressor gene FBXW7 or ERK1/ERK2 signaling cascade, but also affect breast cancer cell growth and promote epithelial cell transformation through MAPK signaling." (PMID 33005492, 2020). "FBXW7 mRNA expression is lower in breast cancer compared with normal tissues." (PMID 30086763, 2018). "Despite the current lack of clarity regarding the role played by FBXW7 dimers in breast cancer progression, making clear the crosstalk between dimerization in FBXW7 and substrate ubiquitination could provide a potential molecular mechanism for cellular regulation." (PMID 37658431, 2023). "We show that shRNA-mediated knockdown of FBXW7 confers increased lethality to non-transformed MCF10A cells with activated MYCER and to T47D breast cancer cells." (PMID 25669969, 2015).
gastric cancer (98 papers, 2010 to 2026). A primary or metastatic malignant neoplasm involving the stomach. "For example, in gastric cancer, FBXW7 causes apoptosis, arrests growth, and inhibits epithelial-mesenchymal transition by enhancing RhoA ubiquitination and proteasome degradation." (PMID 39823500, 2025). "Meta-analysis and bioinformatics unveiled that FBXW7 expression was associated with gastric cancer prognosis." (PMID 39823500, 2025). "Previous studies indicated that low expression of FBXW7 was a major cause of carcinogenesis and poor prognosis in Gastric cancer, which was consistent with our findings." (PMID 36591289, 2022). "Studies revealed that loss of CDC4/FBXW7 promoted amplification of c-Myc in both early-onset of gastric cancers (EOGC) and conventional gastric carcinogenesis." (PMID 30791487, 2019). "Yakobori found that FBXW7 mRNA expression level was associated with tumor size, lymphatic metastasis and prognosis in gastric cancer." (PMID 28464881, 2017). "In general, Fbxw7 displays a mutation frequency about 6% in multiple human cancers, including gastric cancer." (PMID 28422719, 2017). "Although some studies indicate that low FBXW7 expression is associated with tumor progression and drug resistance in many malignancies, there is a paucity of studies examining FBXW7 in gastric cancer." (PMID 28464881, 2017). "In this study, we demonstrated that low level FBXW7 expression is associated with cancer progression and poor prognosis using a large database in gastric cancer." (PMID 28464881, 2017). "In our study, gastric cancers with low FBXW7 expression was associated with cancer progression and worse prognosis." (PMID 28464881, 2017). "In vitro studies showed that increased MYC and reduced FBXW7 expression is associated with a more invasive phenotype in gastric cancer cell lines." (PMID 24053468, 2013). "The results support that Fbxw7 haploinsufficiency increases the gastric cancer risk." (PMID 28422719, 2017). "In clinical samples, reduced expression of FBXW7 has been reported to be associated with poor prognosis and cancer progression in various human solid cancers, such as gastric cancer, esophageal cancer, colorectal cancer, and cholangiocarcinoma, due to the accumulation of several oncoproteins." (PMID 29348852, 2017). "Furthermore, the loss of FBXW7 has been demonstrated to be related with poor prognosis in colorectal cancer, gastric cancer and IHCC." (PMID 25749036, 2015). "Rescue experiments showed that downregulation of FBXW7 reversed MT1JP-induced inhibition of gastric cancer proliferation, invasion, and migration." (PMID 40534867, 2025). "Mechanistic analysis showed that lncRNA MT1JP recruited miR-92a-3p and upregulated FBXW7 in gastric cancer." (PMID 40534867, 2025). "The BDNF-AS/WD repeat domain 5 (WDR5)/F-box and WD repeat domain-containing 7 (FBXW7) axis regulates ferroptosis in gastric cancer cells by affecting the ubiquitination of voltage-dependent anion channel 3 (VDAC3)." (PMID 38481525, 2024). "In gastric cancer, miR-223 acted as an oncogene and negatively modulated FBXW7 expression, governing proliferation, apoptosis, and invasion." (PMID 37047300, 2023). "Similarly, FBXW7 could also be downregulated by exosomal miR-500a-3p in gastric cancer and is linked to enhanced disease staging, chemoresistance, and poor survival among gastric cancer patients." (PMID 36674525, 2023).
gastric cancer (continued). "In gastric cancer (GC), the downregulated level of FBXW7 attenuated its impact on growth arrest and apoptosis." (PMID 35515121, 2022). "Mechanistical analysis demonstrated that lncRNA MT1JP sponged miR-92a-3p and upregulated FBXW7 in gastric cancer." (PMID 35928868, 2022). "In gastric cancer, lncRNA MT1JP binds miR-92a-3p to regulate FBXW7 expression, which in turn affects gastric cancer progression." (PMID 35646642, 2022). "Circ-FBXW7 is down-regulated in primary patient cells from glioblastoma, colorectal, and gastric cancer samples, and in triple-negative breast cancer cells." (PMID 35346215, 2022). "Although expression of miR-92a-3p is elevated in gastric cancers, the ceRNA activity of lncRNA MT1JP can efficiently prevent miR-92a-3p repression of FBXW7 mRNA expression and induce apoptosis of gastric cancer cells." (PMID 35346215, 2022). "In previous studies, we have confirmed that CCDC65 mediated the ubiquitination degradation of ENO1 by recruiting FBXW7 in gastric cancer." (PMID 35844805, 2022). "A study of gastric cancer patients detected a high frequency of mutations in MLL4, ERBB3, FBXW7, MLL3, mtor(RPTOR), NOTCH1, PIK3CA, KRAS, ERBB4 and EGFR." (PMID 33909629, 2021). "On the other hand, LncRNA MT1JP expression is decreased in gastric cancer, and it inhibits the process of gastric cancer through competitively binding to miR-92a-3p and regulating the expression of FBXW7." (PMID 34789303, 2021). "Functionally, miR-223 enhances doxorubicin resistance in gastric cancer cells by abating F-box and WD repeat domain-containing 7 (FBXW7)." (PMID 34249713, 2021). "Hsa-miR-223 was demonstrated to act as an oncogene in gastric cancer by targeting FBXW7/hCdc4 to regulate cell apoptosis, proliferation and invasion." (PMID 34079579, 2021). "miR-223, which also directly targets FBXW7, has been found to be significantly up-regulated in cisplatin-resistant gastric cancer cells SGC-7901 and BGC-823 as well as in H. pylori-infected gastric cancer tissue." (PMID 33825941, 2021). "It has been also reported that the phosphorylated GFI1 is a substrate of SCF-type ubiquitin ligase FBXW7 in gastric cancer cells." (PMID 34351909, 2021). "Abnormally expressed FBXW7 has been proved in a lot of tumors, for instance, gastric cancer and colorectal cancer." (PMID 32239181, 2020). "In human gastric cancer, miR-223 was found to promote cisplatin resistance in human gastric cancer cells by regulating cell cycle through targeting FBXW7." (PMID 32577098, 2020). "For example, the lncRNA MT1JP regulates FBXW7 as a ceRNA by interacting with miR-92a-3p in gastric cancer." (PMID 33323548, 2020). "For instance, MT1JP functioned as a ceRNA to regulate FBXW7 in gastric cancer via sequestering miR-92a-3p." (PMID 32565736, 2020). "miR-223 induces anti-cancer drug resistance in gastric cancer cells by regulating the expression of F-box and WD repeat domain-containing 7 (FBXW7)." (PMID 32595638, 2020). "Reduced expression of FBXW7 has been reported to be correlated with worse outcomes in several human cancers, including gastric cancer, colorectal cancer, cervical squamous carcinoma, glioma, and prostate cancer." (PMID 30341246, 2019). "The lncRNA MT1JP (metallothionein 1J, pseudogene) increases expression levels of FBXW7 and inhibits proliferation and invasion of gastric cancer cells." (PMID 31248165, 2019). "Low expression of FBXW7 was observed in primary gastric cancer and contributed to the poor survival and minimal response to adjuvant therapy." (PMID 30791487, 2019). "Additional studies show that reduced FBXW7 expression is correlated with lymph node metastasis, tumor size, and poor prognosis in primary gastric cancer." (PMID 30086763, 2018). "miR-223-3p has been characterized as a oncogene in multiple tumors, such as pancreatic cancer, prostate cancer, ovarian cancer, lung cancer and gastric cancer, by targeting different genes, such as FBXW7, SEPT6, SOX11, EPB41L335–38." (PMID 29317648, 2018).
gastric cancer (continued). "In gastric carcinoma, inhibition of miR-25 induces cell apoptosis through up-regulation of FBXW7 and down-regulation of FBXW7 substrates, such as cyclin E and c-Myc." (PMID 30086763, 2018). "The mouse model of Fbxw7 haploinsufficiency is a useful tool for gastric carcinogenesis study, especially for intestinal-type gastric cancer study." (PMID 28422719, 2017). "Recent studies revealed that Fbxw7 regulates apoptosis, growth arrest, and epithelial-to-mesenchymal transition in gastric cancer." (PMID 28422719, 2017). "They found MiR-223 promotes cisplatin resistance in human gastric cancer cells via regulation of the cell cycle by targeting FBXW7." (PMID 28464881, 2017). "By immunohistologic evaluation, low expression of FBXW7 in primary gastric cancer significantly correlated with poor differentiation of tumor cells." (PMID 28464881, 2017). "Yokobori also confirmed that down regulation of Fbxw7 gene expression by RNA interference can lead to c-Myc and cyclin-E accumulation and increased proliferation of gastric cancer cells." (PMID 28464881, 2017). "Recently, several genomic sequencing on gastric cancer revealed that the mutant frequency of Fbxw7 gene was about 6–9%, which further suggested the possible role of Fbxw7 gene on gastric carcinogenesis." (PMID 28422719, 2017). "Fbxw7 gene alteration has been found in a variety of tumors, such as lymphoma, glioma, colorectal cancer and gastric cancer." (PMID 28422719, 2017). "The results suggested that the lower expression of Fbxw7 and the higher incidence of gastric cancer were attributed to the Fbxw7 haploinsufficiency." (PMID 28422719, 2017). "Increased miR-363 expression promotes gastric cancer cell proliferation and chemo-resistance through directly targeting the tumor suppressor F-box and WD repeat domain-containing 7 (FBW7)." (PMID 27167197, 2016). "Reduced Fbxw7 expression is often observed in multiple human cancers including breast cancer, colorectal cancer, gastric cancer, prostate cancer, pancreatic cancer and HCC (Hepatocellular carcinoma)." (PMID 24884509, 2014). "miR-223 targets FBXW7/hCdc4 expression at the post-transcriptional level and appears to regulate cellular apoptosis, proliferation, and invasion in gastric cancer." (PMID 23826080, 2013). "Downregulation of Fbxw7/hCdc4 expression has been reported in glioma, gastric cancer and colorectal, but the mechanism(s) responsible for loss of expression of Fbxw7/hCdc4 in cancer is not known." (PMID 21122106, 2010). "MT1JP regulates gastric cancer progression by binding to miR-92a-3p competitively with FBXW7." (PMID 35430805, 2022). "lncRNA MT1JP functioned as a ceRNA to regulate miR-92a-3p/FBXW7 in gastric cancer." (PMID 35936736, 2022). "Thus, the tumor suppressor FBXW7 affects the proliferation/survival of gastric cancer cells, and can be regulated following infection and chemotherapeutic treatment." (PMID 33825941, 2021). "MiR-223-3p and FBXW7 also act as a target in gastric cancer." (PMID 33777092, 2021). "MT1JP, which severs as a ceRNA regulating FBXW7 expression, could influence the progression of gastric cancer." (PMID 34196116, 2021). "Besides, we unveiled that LH reduced the protein stability of MCL1 by up-regulating ubiquitin E3 ligase FBXW7, arrested cell cycle at S phase and triggered apoptosis of gastric cancer cells." (PMID 33126914, 2020). "After down-regulating FBXW7 in the gastric cancer cells, we found that the down-regulation of MCL1 expression induced by LH could be partially restored." (PMID 33126914, 2020). "RhoA-mediated Fbxw7 regulates the apoptosis of tumor cells and other phenotypes in gastric cancer." (PMID 32831016, 2020). "Similarly, in gastric cancer, miR-223 functions an oncogene and found to negatively regulate FBXW7 expression that governs the cellular apoptosis, proliferation, and invasion." (PMID 30791487, 2019). "miR-223 is found to promote cisplatin resistance of human gastric cancer cells by targeting FBXW7." (PMID 30086763, 2018).
gastric cancer (continued). "FBXW7 R465C (GCG > GTG), was associated with MMR signatures in both colorectum and stomach cancer." (PMID 29748584, 2018). "Overall, these studies suggest that FBXW7 may play an important role in chemotherapy resistance in cancers including gastric cancer." (PMID 28464881, 2017). "A reduced expression of Fbxw7 is detected in gastric tumors compared to the paired non-neoplastic specimens and is associated with a highly invasive phenotype in gastric cancer cell lines." (PMID 28422719, 2017). "Demethylzeylasteral promotes the degradation of c‐Myc through up‐regulating the expression level of FBXW7 (an E3 ubiquitin ligase) and consequent ubiquitylization of c‐Myc, which in turn inhibits cell proliferation, migration and invasion, and therefore, depresses the growth of gastric cancer." (PMID 34766156, 2021). "MiR-25, miR-141 and miR-223, which are significantly up-regulated in SGC-7901/DDP resistant gastric cancer cells, could enhance DDP resistance via suppressing expression levels of FOXO3a, kelch-like ECH-associated protein-1(KEAP1) and F-Box and WD repeat domain containing 7 (FBXW7), respectively." (PMID 32192494, 2020). "Similarly, oncogenic miR-223 could decrease trastuzumab sensitivity of gastric cancer through suppressing expression of FBXW7." (PMID 32192494, 2020). "The overexpression of miR-223 in gastric cancer cells also attenuated the level of FBXW7, thereby increasing the GC cell proliferation, invasion and induced chemoresistance to trastuzumab in vitro." (PMID 30791487, 2019). "Moreover, MT1JP regulates FBXW7 and inhibits gastric cancer via binding to miR-92a-3p." (PMID 31248165, 2019). "In previous studies, low expression of FBXW7 in cancer tissue was found to be associated with poor prognosis and cancer progression in several solid cancers, including gastric cancer, colorectal cancer, esophageal cancer, non-small cell lung cancer, cholangiocarcinoma, and hepatocellular carcinoma." (PMID 29348852, 2017). "In addition, lncRNA-MT1JP has emerged as a potential therapeutic target by competitively binding to miRNAs in gastric cancer and regulating FBXW7 expression, and has emerged as an important epigenetic regulator that plays a key role in GC." (PMID 41542087, 2025). "It was found that the LncRNA BDNF-AS regulates the transcription of the FBXW7 promoter by WDR5 methylation of its CpG island, and then FBXW7 regulates the expression of the VDAC3 protein by ubiquitination in gastric cancer cells." (PMID 40191204, 2025). "It is also found that FBXW7 suppresses gastric cancer (GC) metastasis by inducing Brg1 degradation." (PMID 36998461, 2023). "Even more, miR-223, miR-363 and miR-500a-3p directly targeted F-box and WD repeat domain containing 7 (FBXW7) and promote DDP-resistance in gastric cancer cells." (PMID 35444536, 2022). "Rescue experiments exhibited that downregulation of FBXW7 reversed MT1JP-induced inhibition of proliferation, invasion and migration in gastric cancer." (PMID 35928868, 2022). "In gastric cancer, lncRNA MT1JP as ceRNA sponges miR-92a-3p to regulate the expression of FBXW7 and then influence the progression of gastric cancer." (PMID 33968763, 2021). "In gastric cancer, lncRNA MT1JP regulated the expression of FBXW7 through competitively binding with miR-92a-3p, and played a role in inhibiting cell proliferation, migration, invasion and promoting cell apoptosis." (PMID 32661236, 2020). "For example, FBXW7 overexpression can lead to the reduction in cell proliferation, migration and invasion in renal cancer, HCC, and gastric cancer." (PMID 32159214, 2020). "AMPK has been shown to increase the expression of tumor suppressor genes including F-box and WD repeat domain containing 7 (FBXW7), semaphorin III/F (SEMA3F), and p21Cip1 (p21) in gastric cancer cells, and RORα functions a transcription activator." (PMID 28052040, 2017).